HMBOX1 (homeobox containing 1)
Diseases named in the same sentence as HMBOX1 in open-access papers (continued):
Sharing a sentence is not in itself a finding about the gene and the disease.
cancer (12 papers, 2014 to 2025). A tumor composed of atypical neoplastic, often pleomorphic cells that invade other tissues. "As well, telomere length is well known to play a crucial role in cancer cell survival and, recently, m6A was implicated in the regulation of telomere metabolism by downregulating HMBOX1, a telomeric DNA-binding protein." (PMID 39300486, 2024). "dCas13b-METTL3, a m6A editing tool based on CRISPR system, proves that METTL3-catalyzed HMBOX1 methylation is involved in regulating telomerase recruitment, resulting in telomere loss in cancer cells, and m6A is involved in carcinogenesis." (PMID 37519297, 2023). "HMBOX1 mRNA is highly methylated at N6‐adenosine (m6A) in cancer cells, resulting in chromosome abnormalities and aggressive phenotypes." (PMID 40008841, 2025). "Previously, METTL3‐catalyzed m6A in HMBOX1 mRNA was shown to induce genomic instability in cancers by disrupting telomere homeostasis." (PMID 40008841, 2025). "For example, downregulation of homeobox-containing 1 (HMBOX1) can promote cancer cell proliferation and migration in HGSOC." (PMID 34341710, 2021). "HMBOX1 has been identified as a potential biomarker for various cancers." (PMID 40008841, 2025). "HMBOX1 mRNA has been identified as the real target of m6A modification in cancer cells." (PMID 39054967, 2024). "Recent studies demonstrated the dysregulated HMBOX1 in various cancers." (PMID 32814762, 2020). "The finding that HMBOX1 supports telomerase-dependent telomere elongation might indicate the possible critical role of HMBOX1 in cancer pathogenesis." (PMID 25133526, 2014). "Notably, HMBOX1 mRNA has been identified as a de novo target for m6A modification in cancer cells." (PMID 36446846, 2022). "Transcription factors such as HMBOX1, DDX5, and ZBTB5, which were identified to be co-regulated by miR-20a and miR-15b, have implication on cancer progression." (PMID 31602261, 2019). "Mechanistically, BP induces ferroptosis through both canonical (ROS accumulation and GPX4 inhibition) and non-canonical (HMBOX1-mediated) pathways, effectively targeting both bulk tumor cells and cancer stem cells." (PMID 41049453, 2025). "Homeobox-Containing 1 (HMBOX1, also known as HOT1 or TAH1) is a mammalian telomere-binding protein that is involved in the recruitment of active telomerase and is required for telomere maintenance in the alternative lengthening of telomeres (ALT) in cancer cells." (PMID 36446846, 2022).
tumor (11 papers, 2010 to 2025). "In a previous study, the expression of the transcription factor HMBOX1 was shown to be markedly lower in HGSOC cells than in normal ovarian epithelial cells, and HMBOX1 was shown to impede tumor progression by curbing immune evasion." (PMID 40265011, 2025). "HMBOX1 expression was significantly reduced with tumor size and metastasis." (PMID 32814762, 2020). "Common up-regulated genes are related to transcription regulation (HMBOX1, LINC00340, NEXN-AS1), immune response (CD86, IL6, IFIT2) and the last two are potential tumor suppressors (LRRC2 and SPINK6)." (PMID 28035074, 2017).
infection (2 papers, 2021 to 2024). The state of being infected such as from the introduction of a foreign agent such as serum, vaccine, antigenic substance or organism. "We further identify several TFs which are not, in healthy cells, specific to any immune cell type, but are predicted to have cell type-specific changes to TF activity during infection (e.g., HMBOX1, ZNF24, ZNF691)." (PMID 38238840, 2024). "In the process of cross-species infection by the influenza virus, ssc-miR-221-3p and ssc-miR-222 can induce the apoptosis of positive allosteric modulators (PAM) cells by directly targeting the mRNA of HA and PA genes and the expression of the anti-apoptotic protein HMBOX1." (PMID 35062254, 2021).
HMBOX1 also shares sentences with these, for which no sentence is quoted: anaplastic glioma (1 paper); atherosclerosis (1); immune diseases (1); Ovary Adenocarcinoma (1).